MMP9 (matrix metallopeptidase 9)
Diseases named in the same sentence as MMP9 in open-access papers (continued):
Sharing a sentence is not in itself a finding about the gene and the disease.
esophageal cancer (continued). "After neoadjuvant RCT of esophageal cancer patients MMP-9 levels increased in the proximal and even distal healthy esophageal tissue, which could be associated with post-operative complications such as anastomotic leakage, and could potentially be avoided by MMP-9 inhibition." (PMID 34055644, 2021). "Similarly, El-Kenawy 's study also showed MMP9 positively correlated with MVD in esophageal cancer." (PMID 28423526, 2017). "Since MMP-2 and MMP-9 promotes cell migration and invasion, this may be possible mechanism in which hUCMSCs promote esophageal carcinoma cells invasion and thus may be a possible explanation for hUCMSCs promoted the lymph node metastasis of esophageal cancer." (PMID 25298750, 2014). "KRT80 silencing reduced the expression of MMP-9, which account for the promoting effects of KRT80 on the invasion and metastasis of esophageal cancer cells." (PMID 38241178, 2024). "We also reveal that in esophageal cancer cells, SO effectively reduces the production of lactic acid, which, as we have shown, synergizes the stimulating effect of TNF-α on MMP9 expression." (PMID 36555705, 2022). "For example, MMP9 neutralizing antibody (andecaliximab) and anti-PD1 (nivolumab) was combined to treat gastric and esophageal cancers in the phase II clinical trial NCT02864381, suggesting the potential re-application of MMP inhibitors in cancer therapy." (PMID 32988398, 2020). "Overall, the outcomes of this study implicate that Snail-1 knockdown utilizing siRNA can significantly interrupt esophageal cancer cell migration and reduce metastatic-related factors, vimentin, CXCR4, MMP-9, and induce miR-34a and let-7a in vitro." (PMID 30276140, 2018). "The anti-migratory activities and suppressive effects on metastasis-related factors such as HER2, MMP2, MMP9, TM4SF3, CXCR4 of the absorbed AP components were revealed in esophageal cancer cells EC-109." (PMID 28405006, 2017). "Using an esophageal cancer cell line, te-1, it was possible to show that PLGF stimulates MMP9 expression in esophageal cancer cells and PLGF-positive esophageal cancer cells grow when transplanted into recipient mice, where they grow much faster than PLGF-negative cells." (PMID 28930282, 2017). "In line with this hypothesis, Chen and coworkers observed higher levels of Placental Growth Factor (PLGF) and Metalloproteinase (MMP9) in metastatic than in non-metastatic esophageal cancer." (PMID 28930282, 2017).
cholangiocarcinoma (33 papers, 2009 to 2025). A carcinoma that arises from the intrahepatic biliary tree (intrahepatic cholangiocarcinoma) or from the junction, or adjacent to the junction, of the right and left hepatic ducts (hilar cholangiocarcinoma). "Silencing of LCN2 represses invasion through a reduction in LCN2/MMP-9 complex formation in cholangiocarcinoma cells, which is linked to reduced survival of patients with cholangiocarcinoma of higher LCN2 expression." (PMID 34202288, 2021). "RKIP is negatively associated with cholangiocarcinoma distant metastasis and prevents cholangiocarcinoma cell metastasis through downregulating MMP-9 expression and upregulating TIMP-4 expression." (PMID 25435928, 2015). "MMP2 and MMP9 are key enzymes involved in extracellular matrix degradation, promoting tumor invasion, metastasis, and angiogenesis in cholangiocarcinoma." (PMID 41300430, 2025). "Collectively, MMP2 and MMP9 serve as both prognostic biomarkers and potential therapeutic targets in cholangiocarcinoma." (PMID 41300430, 2025). "A novel therapeutic approach by use of a certain antineoplastic agent with effects on MMP-9 activity suppression in cholangiocarcinoma cells was reported." (PMID 36837539, 2023). "Chan-on (2015) reported that nitroxoline significantly suppresses the cell migration and decreases the expression of MMP-2 and MMP-9 in cholangiocarcinoma cells." (PMID 33046984, 2020). "In vivo studies have shown that TNF‐a can induce the overexpression of MMP9 in cholangiocarcinoma cell lines." (PMID 32735065, 2020). "To identify the mechanism underlying the effects of β6 on invasion in cholangiocarcinoma cells, we measured the mRNA expression of uPA, MMP2, MMP3, and MMP9 using quantitative real-time PCR after silencing or overexpressing β6." (PMID 27440504, 2016). "Our previous work showed that β6 induced the expression of MMP9 and promoted the invasiveness of cholangiocarcinoma cells in a Rac1-dependent manner." (PMID 27440504, 2016). "We found that β6-specific siRNA significantly downregulated MMP9 mRNA expression in cholangiocarcinoma cells, and β6 overexpression markedly increased MMP9 mRNA expression." (PMID 27440504, 2016). "We further explored the effect of β6 on secreted MMP9 in the supernatant of cholangiocarcinoma cells by ELISA." (PMID 27440504, 2016). "RKIP inhibits cholangiocarcinoma cell invasion and migration via downregulating MMP-9 expression and upregulating TIMP-4 expression." (PMID 25435928, 2015). "In the present study, RKIP was revealed to inhibit the invasion and metastasis of cholangiocarcinoma cells by downregulating MMP-9, but upregulating TIMP-4 mRNA expression." (PMID 25435928, 2015). "The induction of MMP-9 by PGE2 in TNF-α treated cholangiocarcinoma cells has been reported to occur through the activation of EP2/4 receptors." (PMID 25595899, 2015). "The present study demonstrated that RKIP overexpression significantly inhibits MMP-9 expression, indicating that RKIP reduces the invasiveness of cholangiocarcinoma RBE cells by downregulating MMP-9 expression." (PMID 25435928, 2015). "It has been previously reported that tumor necrosis factor α-induced MMP-9 production in cholangiocarcinoma (CC) cells is concurrent with enhanced fascin-1 expression." (PMID 24993803, 2014). "Our study showed that EGCG inhibited invasion and migration of HuCC-T1 human cholangiocarcinoma cells and suppressed MMP-9 activity." (PMID 23864881, 2013). "Previous studies have demonstrated that matrix metalloproteinase (MMP)-7 and MMP-9 are frequently expressed in cholangiocarcinoma specimens." (PMID 19405942, 2009). "We measured the level of CEA, CA19-9, MMP-7 and MMP-9 in the serum of 44 cholangiocarcinoma and 36 benign biliary tract diseases patients." (PMID 19405942, 2009). "The role of circulating MMP-9 in diagnosing cholangiocarcinoma should be further investigated by collecting the plasma instead of serum and the assay should be performed without long delay." (PMID 19405942, 2009).
cholangiocarcinoma (continued). "MMP-9 was already proven as an invasion and migration factor of cholangiocarcinoma cells." (PMID 36837539, 2023). "Consistent with the results from the mRNA analysis, the data showed that the secreted MMP9 in the supernatant of cholangiocarcinoma cells was significantly decreased after suppression of β6 expression, while β6 overexpression increased MMP9 secretion in the supernatant." (PMID 27440504, 2016). "Furthermore, TNF-α stimulation was shown to induce over-expression of fascin that in turn up-regulate MMP-9 expression in cholangiocarcinoma." (PMID 22076152, 2011). "This study was designed to determine whether the serum levels of MMP-7 and MMP-9 can discriminate cholangiocarcinoma patients from benign biliary tract disease patients in comparison to carcinoembryonic antigen (CEA) and carbohydrate antigen 19-9 (CA19-9)." (PMID 19405942, 2009). "In addition, we also found that the accuracy of the serum MMP-7 level for the diagnosis of cholangiocarcinoma is better than the serum level of MMP-9, CEA and CA19-9, as observed by calculating the AUC of the ROC curve." (PMID 19405942, 2009). "One such secretome biomarker present in the bile secreted by the cholangiocarcinoma is the neutrophil gelatinase-associated lipocalin (NGAL), a 25-kDa glycoprotein that forms a covalently linked complex with the 92-kDa type-IV gelatinase matrix metalloproteinase-9 (MMP9)." (PMID 37835806, 2023). "Collectively, these findings highlight tiliacorinine’s strong binding affinities to pivotal cholangiocarcinoma-related targets, including MTOR, SRC, MMP9, and MAPK1, underscoring its potential as a promising multi-target therapeutic candidate." (PMID 41300430, 2025). "RKIP inhibited the invasive and metastatic ability of the cholangiocarcinoma cell line, RBE, by downregulating MMP-9 and upregulating TIMP-4 mRNA expression." (PMID 25435928, 2015). "In cholangiocarcinoma cell lines, S100A4-silencing leads to reduced motility, invasiveness, and MMP-9 secretion in vitro." (PMID 23166536, 2012). "Among the serum levels of CEA, CA19-9, MMP-7 and MMP-9, only the serum MMP-7 level was significantly higher in the patients with cholangiocarcinoma (8.9 ± 3.43 ng/ml) compared to benign biliary tract disease patients (5.9 ± 3.03 ng/ml) (p < 0.001)." (PMID 19405942, 2009). "Previous studies have demonstrated that the expression of MMP-9 and MMP-7 can be detected in cholangiocarcinoma specimens." (PMID 19405942, 2009). "In addition, capsaicin suppressed the migration and invasion of cholangiocarcinoma cells by inhibiting NF-κB via AMPK-SIRT1 and AMPK-IκBα signaling pathways, leading to the suppression of matrix metalloproteinase-9 (MMP-9) expression." (PMID 29854630, 2018). "To determine whether the values of serum MMP-9 and MMP-7 were predictive of cholangiocarcinoma independently of other tumor markers, we carried out a logistic regression analysis." (PMID 19405942, 2009). "Due to the significant difference of the serum AST, ALP, total bilirubin and direct bilirubin between the control and cholangiocarcinoma patients, we investigated the correlation between the values of these blood chemistries and the values for CEA, CA19-9, MMP-9 and MMP-7." (PMID 19405942, 2009). "Therefore, in our study, the accuracy of serum MMP-9 and MMP-7 levels were investigated in an effort to find a reliable serum marker that can discriminate the benign biliary tract diseases from cholangiocarcinoma." (PMID 19405942, 2009). "Therefore, miR-186 targets Twist1 to inhibit the expression of N-cadherin, vimentin, and matrix metallopeptidase 9 (MMP9), as well as increase the expression abundance of E-cadherin to inhibit the proliferation, migration, invasion, and EMT of cholangiocarcinoma cells." (PMID 35805066, 2022). "Therefore, detection of MMP-9 and MMP-7 in the blood circulation may be useful for the clinical diagnosis of cholangiocarcinoma." (PMID 19405942, 2009).
cholangiocarcinoma (continued). "Likewise, a series of experiments performed in this study suggest that Huaier alone or combined with 5-FU could inhibit the invasion and metastasis of cholangiocarcinoma cells and those involved in the down-regulation of N-cadherin, Vimentin, MMP-2 and MMP-9 expression." (PMID 31391034, 2019). "In cholangiocarcinoma (CCA) cells, magnolol significantly inhibits cell growth, migration, and invasion, accompanied by decreased expression of Ki67, proliferating cell nuclear antigen (PCNA), matrix metalloproteinases 2 (MMP-2), MMP-7, and MMP-9." (PMID 31240205, 2019). "Our results showed that β6 induced the expression of MMP9 but not that of uPA, MMP2 or MMP3 in cholangiocarcinoma cells." (PMID 27440504, 2016). "To date, there is no published study on the detection of serum levels of MMP-9 and MMP-7 in cholangiocarcinoma patients." (PMID 19405942, 2009). "The objective of this study was to determine the accuracy of detecting serum levels of MMP-9 and MMP-7 for the diagnosis of cholangiocarcinoma in patients without primary sclerosing cholangitis." (PMID 19405942, 2009).
autoimmune disease (32 papers, 2005 to 2026). A disorder resulting from loss of function or tissue destruction of an organ or multiple organs, arising from humoral or cellular immune responses of the individual to their own tissue constituents. "T1DM is associated with autoimmune diseases, and both upregulation and downregulation of MMP-9 have been reported in a variety of diseases with autoimmune origin." (PMID 39685536, 2024). "As MMP9 levels were reported to be associated with pulmonary involvement in the progression of autoimmune diseases, myositis patients were further sub-classified into the ILD and non-ILD groups, according to the presence of ILD." (PMID 31440381, 2019). "Matrix metalloproteinase-9 (MMP-9) has been implicated in the pathogenesis of cancer, autoimmune disease, and various pathologic conditions characterized by excessive fibrosis." (PMID 15642145, 2005). "It is noteworthy that while MMP-9 has several important physiological functions, it can, under some circumstances, contribute to pathological conditions such as autoimmune disease and cancer." (PMID 40535580, 2025). "MMP9 contributes to the development of chronic inflammatory and autoimmune diseases, and plays a crucial role in hormone regulation and the maintenance of ovarian function." (PMID 39850756, 2024). "High serum levels of neurofilament protein light subunit (NFL), high mobility group box 1 (HMGB1), Matrix metalloproteinase-9 (MMP-9) and have been reported in several autoimmune diseases." (PMID 38463908, 2024). "Increasing levels of MMP-9 are involved in various processes containing inflammation, autoimmune disorders, and degenerative diseases, which should also be taken into account." (PMID 37175113, 2023). "Just like MMP-8, MMP-9 is another important enzyme that plays a part in multiple autoimmune diseases." (PMID 36221125, 2022). "At the same time, MMP9 has been found in a number of autoimmune diseases and biological processes, such as pulmonary inflammation, hemorrhage, infection and cancer." (PMID 34239024, 2021). "MMP9 has emerged as a key factor in the pathogenesis of autoimmune diseases and is involved in small-vessel vasculopathy." (PMID 31440381, 2019). "One enzyme of extracellular proteolysis is of particular interest in inflammatory and autoimmune diseases: gelatinase B or matrix metalloproteinase-9 (MMP-9)." (PMID 30449890, 2018). "Recently, a convincing support for the involvement of MMP-9 in inflammation, autoimmune diseases, cancer metastases and physical injuries has been reported." (PMID 24633733, 2015). "Matrix metalloproteinase-9 (MMP-9) has been postulated with the pathogenesis of autoimmune diseases including SLE." (PMID 23555760, 2013). "Among the MMPs, MMP-9 has been shown to be involved in a variety of pathological processes of autoimmune diseases." (PMID 21054849, 2010). "Among these, IL-17 stands out as a consistently elevated and mechanistically important cytokine, known to induce fibroblast activation and upregulate MMP-9, thereby contributing to inflammatory and autoimmune diseases, such as Sjogren’s syndrome, as well as KC and DED." (PMID 40993744, 2025). "Furthermore, IL-8 increases the level of MMP-9 in the context of the autoimmune disease Epidermolysis Bullosa Simplex." (PMID 34287260, 2021). "CBP EVs contain critical components for immunosuppression and that CBP EV mimics, specifically those expressing MMP-9 and HSP-72, may offer a novel promising strategy for the treatment of various autoimmune diseases." (PMID 32308765, 2020). "The role of MMP9 in infectious and autoimmune diseases was not clear, research with inconsistent reports." (PMID 25547181, 2014). "Thus, targeting MMP‐9 activity could potentially be a promising candidate in the fight against SLE and possibly other autoimmune diseases." (PMID 28444759, 2017).
brain tumors (32 papers, 2009 to 2025). "Strong up-regulation of MMP-9 protein associated with astrocytes was observed in the immediate vicinity of extravasating cancer cells, and is known to promote growth of primary brain tumors by releasing vascular endothelial growth factor (VEGF) sequestered in the surrounding matrix." (PMID 24324647, 2013). "Despite its potential as a tumor progression biomarker and the growing need for non-invasive methods to monitor brain tumor recurrence, such as liquid biopsy, only a few clinical trials have assessed MMP-9 in this context." (PMID 41573658, 2025). "Research has increasingly shown that MMPs, particularly MMP-2 and MMP-9, influence immune cell trafficking, cytokine release, and immune suppression in brain tumors, potentially by modulating the expression and activity of immune checkpoint molecules." (PMID 40265458, 2025). "The aim of our comparative study was to evaluate the possible additional utility of the MMP-9 level of serum-derived small extracellular vesicles (sEVs) for characterising brain tumours." (PMID 36765669, 2023). "According to our knowledge, this was the first study that investigated the MMP-9 level of serum sEVs in human brain tumours." (PMID 36765669, 2023). "Matrix metalloproteinase-9 (MMP-9) degrades the extracellular matrix, contributes to tumour cell invasion and metastasis, and its elevated level in brain tumour tissues indicates poor prognosis." (PMID 36765669, 2023). "In this study, PCT, HBP, and MMP-9 levels were significantly lower than before treatment after 3, 7 and 10 d in those with intracranial infection secondary to brain tumour surgery and tended to decrease over time." (PMID 36159580, 2022). "It is suggested that PCT, HBP, and MMP-9 tests are potentially valuable in the early diagnosis of intracranial infection after brain tumour surgery." (PMID 36159580, 2022). "Gelatinase-A (MMP-2) and gelatinase-B (MMP-9) are highly expressed in patients with WHO grade III brain tumors." (PMID 32152825, 2020). "This is in keeping with the results of a previous study, which detected MMP-9 in the CSF of 10/15 adult brain tumor patients with positive CSF cytology, compared to 0/27 controls." (PMID 24400253, 2013). "The authors also noted elevations of MMP-9 in the CSF of brain tumor patients relative to controls (p < 0.05)." (PMID 24400253, 2013). "Recently, Smith and coworkers reported significant elevations in MMP-9 and MMP-9/NGAL in brain tumor patients." (PMID 19889214, 2009). "Compound K was also found to have antiangiogenic activities in a spontaneous metastasis model, and to inhibit the expression of matrix metalloproteinase (MMP)-9, which regulates the growth and invasiveness of brain tumors." (PMID 20017956, 2009). "Evaluation of MMP-9 and MMP-9/NGAL complex in urine of patients with brain tumors revealed significantly higher expression levels compared to controls, which was also confirmed in tumor tissue." (PMID 19889214, 2009). "Matrix metalloproteinase-9/neutrophil gelatinase-associated lipocalin (MMP-9/NGAL) complex activity is elevated in brain tumors and may serve as a molecular marker for brain tumors." (PMID 26663949, 2015). "However, the expression levels of miR-211 remained low in the MMP-9 overexpression construct (MMP-9 OE) treated intracranial mice brain tumors." (PMID 23183822, 2012). "Interestingly, the intracranial brain tumors treated with shRNA specific for MMP-9 (pM) showed noticeably increased miR-211 levels." (PMID 23183822, 2012). "Similarly, in the case of the association of the MMP-9-1562C/T polymorphism with an increased risk of brain tumors, there are not enough studies to draw any conclusions." (PMID 37206663, 2023). "However, the relationship between MMP-9/NGAL activity in brain tumors and patient prognosis and treatment response remains unclear." (PMID 26663949, 2015).